APOE (apolipoprotein E)
Diseases named in the same sentence as APOE in open-access papers (continued):
Sharing a sentence is not in itself a finding about the gene and the disease.
Alzheimer disease (continued). "Exercise prevents these changes, but not in the absence of APOE, opening up new avenues for understanding the complex interactions between neurovascular and neuroinflammatory responses in aging and neurodegenerative diseases such as Alzheimer’s disease." (PMID 26512759, 2015). "Notably, the complete lack of lipoprotein clearance in the apoE mice affects other anti-inflammatory and immunomodulatory properties, and these mice also develop diabetes and Alzheimer’s dementia." (PMID 25972522, 2015). "It is in line with the hypothesis that APOE is more important for the development rather than for the progression of Alzheimer's disease." (PMID 24228185, 2013). "However, APP, Presenilin1/2, tau, Apolipoprotein E, Cdk5, TDP-43 or GSK-3beta, which are implicated in Alzheimer's disease and tauopathy, were not included in these results." (PMID 21731734, 2011). "It further suggests that the presence or absence of the APOE ε4 allele may influence the neural and cognitive profiles of individuals with MCI, which could be important for early diagnosis and personalized treatment approaches for Alzheimer’s disease." (PMID 41583006, 2025). "Next, because only APOE genotyping was available in MAS, rare genetic variants associated with Alzheimer’s disease (e.g., TREM2, PSEN1, and other SNPs) were not assessed, and therefore associations between subjective concern trajectories and these genetic mechanisms could not be examined." (PMID 41374454, 2025). "Furthermore, we did not test for Alzheimer's disease-related genes such as the APOE." (PMID 39974219, 2025). "Moreover, APOE ε4 carriers progress more rapidly from mild cognitive impairment (MCI) to Alzheimer’s disease dementia than non-carriers, although the precise pathophysiology of this risk remains unclear." (PMID 40671162, 2025). "Genetic risk factors, including APOE ε4 status, were not available in the NHANES dataset and thus could not be included as covariates, limiting our ability to fully control for potential confounding by genetic predisposition to Alzheimer’s disease." (PMID 40517083, 2025). "The functional differences between ApoAI and ApoE in blood and cerebrospinal fluid (CSF) are not well studied, and it remains unclear whether these apolipoproteins in the periphery and CNS play distinct roles in the pathogenesis of Alzheimer's disease (AD)." (PMID 40353050, 2025). "In humans, KL-VS heterozygosity has been associated with a reduced burden of amyloid and tau pathology in Alzheimer’s disease (AD), potentially offsetting the negative effect of apolipoprotein E (APOE)-ε4 carrier status, one of the most well-established genetic risk factors for AD." (PMID 41393109, 2025). "To examine whether the effect was dependent on APOE status, we repeated the analysis in participants with above-median MR– PRS or above-median more comprehensive PRS (including 1,092,011 SNPs) derived from the largest available Alzheimer’s disease GWAS24 and excluded the APOE area from these PRSs." (PMID 37118290, 2022). "However, the relationship between the peripheral HDL functional capacity and Alzheimer’s disease has not been fully investigated in a larger cohort of Alzheimer’s disease patients, and the effects of the APOE genotype on this relationship have not been investigated." (PMID 35884800, 2022). "However, results from Alzheimer’s Disease Neuroimaging Initiative (ADNI) cohorts and Uniform Data Set of the Alzheimer’s Disease (UDS) Centers and Australian Imaging, Biomarkers and Lifestyle Flagship Study of Ageing (AIBL), both demonstrated significant correlations between APOE ε4 and aging." (PMID 35720695, 2022). "Although we accommodate APOE status and CSF biomarker levels in our analysis, we did not specifically stratify our subjects based on amyloid positivity, under the emerging concept that amyloid facilitates rather than governs the spatiotemporal trajectory of Alzheimer’s disease spectrum subjects." (PMID 34704025, 2021).
Alzheimer disease (continued). "Another notable finding was that APOE ɛ4 predicted slope but not level of cognitive performance in this study group, and that the effect on slope was only seen when including the last test occasion where the probability of individuals being at a preclinical stage of Alzheimer’s disease was higher." (PMID 32709845, 2020). "However, not everyone with the APOE e4 gene will develop Alzheimer disease, and having the APOE e2 gene, which confers resistance to Alzheimer disease, is likewise not a guarantee that one will never get Alzheimer disease." (PMID 31610629, 2019). "This was true across all subgroups of older adults, regardless of Aβ and ApoE status, although desegregation was greater in older subgroups without Aβ compared to those with Aβ which may be indicative of divergent process of aging and Alzheimer's disease." (PMID 29527500, 2018). "Taken together, these results and that of the present study suggest that higher education may offset the negative effects of the APOE ε4 on mortality by increasing cerebral reserve capacity against Alzheimer's disease and other late-life cognitive-related diseases." (PMID 29770230, 2018). "Thus, common variation, as with APOE in Alzheimer's disease, rather than a founder effect, could be responsible for sporadic ALS." (PMID 20801717, 2010). "A study of 219 cognitively normal adults enrolled in longitudinal aging studies indicated that 51.9% wanted Apolipoprotein E (APOE) genotype, despite the fact that Alzheimer’s disease is non-actionable." (PMID 34748551, 2021). "It has also been shown that among Alzheimer’s disease patients, those who were homozygous for APOE-ε4 had shorter LTL than those who were heterozygous for APOE-ε4 or noncarriers." (PMID 33175128, 2021). "Notably, we found two genes displaying a negative association between Alzheimer’s Disease (including proxy) trait and Lung Squamous Cell Carcinoma model with Chi2 value of -18.3 (APOE) and -22.7 (APOC1) (see TWAS Trait association table at twas-hub.org/genes/APOE/and twas-hub.org/genes/APOC1/)." (PMID 31608105, 2019). "While this may be reasonable for the amyloid+ and APOE+ groups, the wider sporadic Alzheimer’s disease is likely to show more variability in the event sequence due to the inherent disease heterogeneity, driven perhaps by genetic, e.g. the presence or absence of APOE4, or lifestyle factors." (PMID 25012224, 2014). "This project uses fractal dimension of mRNA and coding DNA sequences (CDS) to probe the lncRNAs within the mRNAs (but not the CDS) in Alzheimer's disease genes, namely, APP or AD1, APOE or AD2, PSEN1 or AD3, and PSEN2 or AD4." (PMID 23662159, 2013). "sPRS without APOE is derived from International Genomics of Alzheimer’s Project (IGAP), which records ΔAUC and ΔR2 of 0.051 ± 0.013 and 0.063 ± 0.015 for Alzheimer’s Disease Sequencing Project (ADSP) and 0.060 and 0.086 for Accelerating Medicine Partnership - Alzheimer’s Disease (AMP-AD)." (PMID 37710206, 2023). "In the current study, we determined whether HDL CEC and LCAT activity are altered in a large APOE genotyped cohort of elderly participants clinically diagnosed as either non-demented, MCI, or Alzheimer’s disease dementia (AD)." (PMID 35884800, 2022). "Another recent study showed that APOE ε4 carriers have accelerated breakdown of the blood-brain barrier (BBB) in the hippocampus and medial temporal lobe contributing to cognitive decline independent of Alzheimer’s disease pathology." (PMID 36446774, 2022). "We did not expect that the Alzheimer’s disease PGS would make such a poor prediction of general cognitive slope, especially when APOE e4 status had made a substantial prediction, and SNPs associated with APOE e4 featured prominently in Alzheimer’s GWAS results." (PMID 30760887, 2020).
Alzheimer disease (continued). "To determine whether inflammation contributes to Alzheimer's disease rather than being merely a correlative pathological feature in the AD brain, we and others tested the hypothesis that ACT and/or apoE serve as amyloid catalysts or pathological chaperones." (PMID 22844635, 2012). "Finally, other limitations to the study could be the absence of apolipoprotein E(APOE) status, brain imaging data, or body fluid biomarkers [amyloid-β (Aβ) and tau protein] for Alzheimer’s disease (AD)." (PMID 39588159, 2024). "Overall, differences in correlations of SPARE-AD scores with molecular measures and APOE ε4 were not statistically significant, supporting the notion that the changes in approach, including regressing out brain age in SPARE-AD3, did not diminish its specificity to Alzheimer’s disease." (PMID 35611306, 2022). "An independent study further identified that the clinical spectrum of early Alzheimer’s disease pathology is explained by different biological pathways, in particular, the endocytosis, clathrin/AP2 adaptor complex, and immune response pathways, that are independent of apolipoprotein E (APOE)." (PMID 32367290, 2020). "Mild cognitive impairment subjects from the Alzheimer's Disease Neuroimaging Initiative (ADNI) study were categorized into β-amyloid-low and β-amyloid-high groups, based on quantitative analysis of [18F]florbetapir PET scans, and APOE ε4 non-carriers and carriers based on genotyping." (PMID 24736891, 2014).
dementia (1,881 papers, 2001 to 2026). Loss of intellectual abilities interfering with an individual's social and occupational functions. "P-tau217 associations with MCI or dementia were larger in magnitude for women older than 70 years (P for interaction = .04), APOE ε4 carriers (P for interaction = .02), and White women compared with Black women (P for interaction < .001)." (PMID 41805953, 2026). "We also examined the joint and interactive effects of sex, APOE ε4, and vascular factors on the risk of dementia." (PMID 41536502, 2026). "APOE ε4-the major genetic risk factor for sporadic dementia in European-ancestry populations-has a similar impact on dementia risk in British South Asians." (PMID 42205162, 2026). "In total, 1323 (30%) participants were categorised as Aβ+ on amyloid PET, 3113 (69%) participants reported a family history of dementia, and 1550 (35%) participants carried at least one APOE ε4 allele." (PMID 41569280, 2026). "We performed sex-stratified analyses to examine the associations of blood pressure metrics and APOE ε4 allele with the risk of cognitive decline and dementia." (PMID 41536502, 2026). "It is also possible that underlying dementia is driving the strong association between APOE and delirium observed here." (PMID 41286463, 2026). "Lewy body pathology showed modest APOE associations restricted to limbic/amygdalar-predominant forms and was related to dementia duration, suggesting AD-mediated secondary synucleinopathy." (PMID 41890856, 2026). "We found that APOE-ε4 is a robust genetic risk factor, remaining significant after adjustment for presence of dementia." (PMID 41286463, 2026). "We next estimated the relative risk of dementia associated with brain ageotypes, stratified by APOE ε4 carriers versus APOE ε3/ε3 carriers." (PMID 41299092, 2026). "In the top quintile of meat consumption, dementia risk and cognitive decline were similar between APOE strata." (PMID 41854609, 2026). "A joint effect of APOE ε4 allele and elevated blood pressure metrics conferred a greater relative excess risk of dementia in women vs. men." (PMID 41536502, 2026). "Using another FHS dataset with 3,048 individuals with genetic data, we examined the association between PCSK9 genotypes and the incidence of AD/dementia, stratifying the analysis based on APOE ε4 status." (PMID 41737429, 2026). "The interaction HR (1.28, 95% CI: 1.02–1.61) suggests that the effect of APOE ε4 carriage on dementia risk is 28% greater when combined with elevated pulse pressure compared to non-elevated pulse pressure." (PMID 41536502, 2026). "Converging evidence indicates that pairing MBI with fluid biomarkers or APOE genotyping enhances early detection and biological profiling of dementia risk." (PMID 41591092, 2026). "Third, the inclusion of APOE genotyping allowed us to evaluate genetic susceptibility and investigate its interaction with vascular risk factors in predicting dementia." (PMID 41536502, 2026). "Among these, APOE‐ε4 consistently emerged as a significant factor associated with poorer cognitive recovery, not only in dementia but also across various types of brain injuries." (PMID 41476008, 2026). "Prediction and prevention studies aiming to use APOE to identify people at high risk of dementia should be inclusive of all ancestries." (PMID 42205162, 2026). "Specifically, our findings demonstrate that women with the APOE ε4 allele and elevated blood pressure metrics have a much higher risk of dementia compared to their male counterparts with the same risk factors." (PMID 41536502, 2026). "We estimated the extents to which clinically diagnosed AD, AD neuropathology and all-cause dementia are attributable to the common APOE alleles in four large studies." (PMID 41522467, 2026). "Despite these contributions, a critical gap remains: most prior studies have not systematically tested for sex differences or examined an overall effect of vascular factors and APOE ε4 on dementia risk in a sample of combined both sexes." (PMID 41536502, 2026).
dementia (continued). "In FinnGen, the same pattern and similar magnitudes of associations of risk of AD and all-cause dementia were observed across APOE genotypes as in UKB, though the association of ε4/ε4 with AD was notably more modest." (PMID 41522467, 2026). "Using latent profile analysis, we resolve distinct lipid states associated with risk and resilience to dementia, modulated by genetic status, sex, and APOE genotype, and supported by concordant changes in circulating protein biomarkers." (PMID 42094071, 2026). "This indicates that the effect of carrying two APOE ε4 alleles on dementia risk was 48% greater in women compared to men." (PMID 41536502, 2026). "The brain age gap predicted future dementia independently of APOE haplotypes, which themselves were strongly associated with dementia risk in a dose-dependent manner." (PMID 41299092, 2026). "In joint-effect analysis, high eGDR (quartile 4) significantly attenuated the association between APOE ɛ4 and dementia/BAG." (PMID 41181882, 2026). "They provide evidence that APOE-ε4 increases the risk for delirium independently of dementia, and highlight potentially clinically relevant plasma proteins." (PMID 41286463, 2026). "To address this, we examined mass-spectrometry-derived proteomic correlates of cognitive function, genetic predisposition to cognitive health, APOE ε4 status, and incident dementia." (PMID 41646675, 2026). "Variants in the APOE region remained significant after adjusting for dementia status in the delirium GWAS." (PMID 41286463, 2026). "Epidemiological data support a dose-response relationship between TBI severity or repetition and subsequent dementia risk, moderated by genetic factors such as apolipoprotein E4 (ApoE4)." (PMID 41683989, 2026). "Specifically, we found that the influence of APOE alleles on dementia risk was most evident among individuals with low social adversity, while among those experiencing high social adversity, APOE genotype had minimal impact." (PMID 41264567, 2025). "In another UK Biobank study, there were stronger associations between multimorbidity and dementia in participants with a lower genetic risk of dementia (defined as non‐carriers of apolipoprotein E ε4)." (PMID 40755143, 2025). "An outlier was the association between two vs zero copies of APOE ε4 on dementia diagnosis, which was stronger among AmEuro-S than AmEuro-N (p<0.05)." (PMID 40791670, 2025). "Among individuals exposed to high social adversity, dementia risk was not only similar across APOE genotypes but also higher than in any other genetic or social adversity group." (PMID 41264567, 2025). "Even among asymptomatic individuals, the presence of a risk APOE genotype and a family history of dementia leads to more divided responses." (PMID 40401661, 2025). "By contrast, the APOE ε4 allele is best known as the major genetic risk factor for Alzheimer’s disease but has also been implicated as a modifier of cognitive decline and dementia risk in PD in multiple studies." (PMID 41326418, 2025). "Another study determined that vascular risk factors increase risk for dementia to a larger extent in APOE ε4 non‐carriers." (PMID 40772428, 2025). "Differences in dementia risk were found between APOE allele profiles in the lowest social adversity level, although these were non-significant." (PMID 41264567, 2025). "In conclusion, our findings demonstrate that the influence of APOE genotype on dementia risk is shaped by social position, consistent with a social-distinction model." (PMID 41264567, 2025). "Among White participants, APOE-ε2 carriers at social advantage presented a lower risk of dementia, and APOE-ε4 carriers at social advantage had a greater risk of dementia than APOE-ε3ε3 carriers at social advantage." (PMID 41264567, 2025). "It was previously shown that CD68 protein levels were increased in APOE e4 allele carriers, and it was strongly associated with dementia and poor cognitive functioning." (PMID 40646278, 2025).